BRAF (B-Raf proto-oncogene, serine/threonine kinase)
Diseases named in the same sentence as BRAF in open-access papers (continued):
Sharing a sentence is not in itself a finding about the gene and the disease.
melanoma (continued). "Such an argument is strengthened by the report from the group of Prof. Erik Sahai on the action of CAFs in conferring resistance to targeted therapies; resistance acquired by BRAF-mutated melanoma cells following PLX4720." (PMID 34680395, 2021). "For example, Vemurafenib (Zelboraf®) targeting BRAF V600E mutant protein is prescribed to treat melanoma patients with BRAF V600E mutation, and imatinib mesylate (Gleevec®) only targets the patients with BCR-ABL fusion proteins in their leukemia cells." (PMID 34575870, 2021). "For example, activating mutations at BRAF codon 600 occur in up to 60% of UV-induced human melanomas, but COMs and derived cell lines are consistently BRAF wild-type." (PMID 34822659, 2021). "The BRAF V600E substitution is the most common driver mutation in superficial spreading melanoma and it accounts for up to 90% of BRAF mutations in cutaneous melanoma, with V600K accounting for a significant remainder." (PMID 35008286, 2021). "Melanoma is the main cause of skin cancer deaths, with special emphasis in those cases carrying BRAF mutations that trigger the mitogen-activated protein kinases (MAPK) signaling and unrestrained cell proliferation in the absence of mitogens." (PMID 33672955, 2021). "Firstly, a large proportion of melanomas (50–65%) are addicted to MAPK signalling through BRAF or NRAS mutations." (PMID 34503064, 2021). "For example, up to half of melanoma cases have been found to harbour activating mutations at BRAF V600, while EGFR mutations have been found to be present in over 30% of NSCLCs." (PMID 34441338, 2021). "Activation of the ISR is correlated with resistance to chemotherapy in pancreatic cancer and BRAF-mutated melanoma." (PMID 34630117, 2021). "The observed associations between expression levels of BANCR and BRAF mutation in the melanoma and papillary thyroid cancer implies the regulatory role of this gene expression of BANCR." (PMID 34409032, 2021). "To uncover potential tumor-intrinsic mechanisms that regulate TLS formation, we have taken the novel perspective of evaluating TLS induction in melanomas impacted by common driver mutations in BRAF, PTEN, NRAS, KIT, PRDM1, and MITF." (PMID 33746966, 2021). "Increased signaling activity of the mitogen‐activated protein kinase (MAPK) pathway is a hallmark of melanoma and can be attributed to mutations in the BRAF, NRAS, KIT, or NF1 genes." (PMID 32767816, 2021). "The study (IMspire150) revealed that atezolizumab was safe and tolerable when combined with vemurafenib and cobimetinib, and substantially improved progression-free survival in patients with BRAF V600 mutation-positive advanced melanoma." (PMID 34804979, 2021). "One documented mechanism of resistance is upregulation of SOX2, a transcription factor that is essential for tumor growth and expansion, particularly in melanoma tumors with BRAF mutations." (PMID 33613844, 2021). "Higher levels of YAP were detected in the majority of NSCLC and melanoma tumors harboring BRAF V600E and NSCLC tumors with KRAS mutations, compared to tumors expressing wild-type BRAF and KRAS." (PMID 33467099, 2021). "Streaks are frequently observed in BRAF mutated melanomas and are considered a sign of tumor growth and proliferation." (PMID 34440462, 2021). "In conclusion, patients with metastatic BRAF-mutated melanoma who progressed on kinase inhibitors and immunotherapy represent a clinical setting with very limited therapeutic options." (PMID 34136385, 2021). "Our findings suggest that PLA1A can be considered as a potential diagnostic marker for advanced and BRAF-mutated melanoma." (PMID 33723350, 2021). "A BRAF.pV600E mutation is frequently present (>80%) both in the melanoma and the nevus from which it arose." (PMID 34449585, 2021). "PLA1A mRNA and serum levels were significantly higher in patients with BRAF-mutated melanoma compared to the patients with NRAS-mutated melanoma." (PMID 33723350, 2021).
melanoma (continued). "Altogether these data support Octpep-1 as an optimal candidate in combination therapies for melanoma BRAF(V600E) mutations." (PMID 33672955, 2021). "Typical driver mutations in melanoma such as BRAF, NRAS, and KIT result in constitutive MEK-ERK-signaling." (PMID 33870460, 2021). "This drug is specifically used in patients with the BRAF V600E mutation, which is found in approximately 60% of melanomas." (PMID 34066301, 2021). "The cited study also proved that the adipokine is committed to determining the aggressive behavior of BRAF-mutated melanomas." (PMID 34068679, 2021). "Approximately 50% of human melanomas are driven by BRAF mutations, characterized by aggressive growth and a highly immunosuppressive tumor microenvironment." (PMID 33407577, 2021). "In this study, we present a patient with pregnancy-associated lymph node metastasis (PALNM) from a BRAF-mutated melanoma." (PMID 34768746, 2021). "Despite the evidence that IDH mutations can confer the in vivo growth ability in melanoma cell lines with BRAF mutations, the biological implications of IDH mutations in melanomas and their impacts on tumorigenesis and progression remain to be elucidated." (PMID 34831002, 2021). "While in melanoma, it is an actionable target for Vemurafenib, BRAF-mutated colorectal cancer is responsive to a regimen involving the combination of encorafenib, cetuximab, and binimetinib." (PMID 33670699, 2021). "He had received three cycles of ipilimumab and nivolumab for recurrent melanoma positive for the BRAF V600E mutation with metastasis to the lungs." (PMID 33810799, 2021). "For example, some melanomas are driven by somatic BRAF gene mutations, and the introduction of effective BRAF inhibitors offered great hope for the treatment of melanoma." (PMID 33555482, 2021). "We now have several different approved regimens, both for targeted therapy for BRAF-mutated melanoma, as well as immunotherapy for all comers with melanoma." (PMID 34571969, 2021). "These NF1 mutations are more common in melanomas occurring on chronically sun-exposed skin or in older patients, in melanomas with higher mutation burden, wild-type for BRAF and NRAS, and in the desmoplastic melanoma subtype." (PMID 34123788, 2021). "BRAF serine/threonine kinase is a proto-oncogene and the activating V600E mutation defines a druggable subtype of melanoma." (PMID 33941236, 2021). "Combination treatment with BRAF (BRAFi) plus MEK inhibitors (MEKi) has demonstrated survival benefit in patients with advanced melanoma harboring activating BRAF mutations." (PMID 34853302, 2021). "The activation of this pathway plays a major role in melanoma oncogenesis, cooperating with BRAF mutations to transform melanocytes." (PMID 34680615, 2021). "The MAPK pathway is almost universally hyperactivated in melanoma, owing to the frequent activating mutations in BRAF and NRAS." (PMID 33808771, 2021). "Here we show that Usp9x plays a key role in SOX2 regulation and in melanoma tumorigenicity, particularly in tumors driven by BRAF mutation and dependent on SOX2." (PMID 33613844, 2021). "MAPK activation has been recognized as a key regulator of tumor biology in malignant melanoma and is the most common dysfunctional pathway within melanoma tumorgenesis, typically via the BRAF or NRAS mutations." (PMID 34155457, 2021). "We compared the results in the UM cell lines with the effect on cell lines with a BRAF or NRAS mutation (i.e. melanoma cell line OCM3 [BRAF-mut] and the CoM cell lines CRMM1 [BRAF-mut] and CRMM2 [NRAS-mut])." (PMID 33798262, 2021). "BRAF‐V600E‐induced autophagy in response to increased ER stress is often a cytoprotective process, and pharmacological inhibition of autophagy was shown to improve the potency of anti‐cancer drugs in melanoma harboring the BRAF‐V600E mutation." (PMID 34355491, 2021).
melanoma (continued). "Trials investigating the effect of drugs specifically targeting BRAFV600E mutants, such as vemurafenib, given as monotherapy, have failed in mut-BRAF colorectal cancers, even though they proved to be effective in melanomas harboring the same mutation." (PMID 34065438, 2021). "Future studies with larger cohorts will be important for studying the incidence of non-V600 BRAF mutations in melanoma patients, and the impact of such mutations on the outcomes of patients with BRAF inhibitor or other targeted therapies." (PMID 33907234, 2021). "Combination therapy with BRAF and MAPK/ERK kinase (MEK) inhibitors, such as trametinib and cobimetinib, is the recommended treatment for BRAF-mutated melanoma." (PMID 34868763, 2021). "Collectively, these observations place the antisenescence transcription factor TBX2 downstream from PI3K signaling that mediates senescence bypass in BRAF mutated melanoma." (PMID 34819350, 2021). "For example, recently study reported that polymethoxyflavones from Gardenia oudiepe (Rubiaceae) induce cytoskeleton disruption-mediated apoptosis and sensitize BRAF-mutated melanoma cells to chemotherapy." (PMID 34475961, 2021). "Oncogenic mutations in the BRAF pathway are the most well-described genetic mutations associated with melanoma development and progression." (PMID 34282258, 2021). "While BRAF mutation testing is recommended for stage III–IV melanoma, guidelines differ in recommending mutation testing in stage II melanoma patients." (PMID 34068774, 2021). "For example, melanoma cells with BRAF mutation often develope drug resistance after treatment with BRAF inhibitors." (PMID 34722635, 2021). "We found that in selected melanoma cells with RAS or BRAF mutations PMCA4b was expressed at low levels." (PMID 33802790, 2021). "Additional examples are HER2 inhibition in breast cancer using lapatinib and/or HER2-specific monoclonal antibodies trastuzumab and pertuzumab or BRAF mutated malignant melanoma using the tyrosine kinase inhibitors vemurafenib or dabrafenib." (PMID 34262462, 2021). "The synergy of Octpep-1 with targeted treatments against mTORC1 and ERK signaling highlights the benefit of combinatorial therapies and the potential of Octpep-1 as an excellent candidate to safely potentiate antitumoral therapies in BRAF-mutated melanoma." (PMID 33672955, 2021). "The hyperactivation of MAPK pathway due to oncogenic mutation of BRAF (Rapidly Accelerated Fibrosarcoma kinase isoform B) occurs in 70% of melanoma cases, 10% of colorectal cases, and 70% of thyroid cancer cases." (PMID 34638829, 2021). "The BRAF V600E mutation is considered as the most common oncogene and precursor in melanoma and is of remarkable value as a therapeutic target." (PMID 33391380, 2021). "Some examples of malignant melanoma arise with the identification of activating mutations in the BRAF oncogene, being one of the most frequent genetic alterations in melanoma (50%)." (PMID 35047063, 2021). "Based on the COSMIC database, more than 10% of BRAF mutations in melanoma are non-V600E mutations and some (i.e., V600R, L597Q/R/S, K601E) have been recently reported to be associated with efficacy of BRAF inhibitor therapy." (PMID 33907234, 2021). "Before starting this treatment, patients must have BRAF V600 mutation-positive melanoma tumour status confirmed by a validated test." (PMID 34790681, 2021). "Such has shown favorable outcomes in treating BRAF-mutated melanomas and colorectal cancers, although drug resistance can eventually develop." (PMID 34429404, 2021). "The BRAF V600E mutation has been reported as a biological marker for aggressiveness and a potential genetic link between malignant melanoma and TC." (PMID 33578751, 2021). "Approximately 50% of melanomas harbor activating BRAF mutations, with 70–90% of these mutations being V600E." (PMID 34537078, 2021).
melanoma (continued). "These alterations seem to vary in frequency depending on the melanoma subtype and are mutually exclusive to BRAF and NRAS mutations, with rare exceptions." (PMID 34831002, 2021). "Mutations in the BRAF gene are closely associated with the development of melanoma, yet most melanoma patients are resistant to BRAF inhibitors." (PMID 34869005, 2021). "Melanoma is an aggressive form of skin cancer that occurs in the melanocytes, caused due to a variety of reasons, often due to the mutations in BRAF, which is responsible for the RAS-RAF-MEK-ERK-MAPK cell signaling pathways." (PMID 37305163, 2021). "The most prevalent form of melanoma with a mutated BRAF gene has an effective treatment, but the second most common mutation in melanoma (NRAS) leads to tumors that lack targeted therapies." (PMID 33921974, 2021). "In 2002, one of the first genomic studies identified mutations in BRAF, a regulator of cell survival, in 65% of malignant melanomas, which led to the development of BRAF inhibitors for BRAF mutant metastatic melanoma." (PMID 34828357, 2021). "Carriers of at least one MC1R variant have a 5- to 15-fold increased risk confined only to BRAF+ melanomas, regardless the presence of chronic solar damage signs." (PMID 34356109, 2021). "The BRAF gene is mutated with a hotspot mutation at codon 600 (mostly V600E) in 40% to 50% of all melanoma cases, followed by NRAS mutations (G12, G13, Q61) in 12% to 20%." (PMID 34768746, 2021). "Common genetic alterations associated with melanoma include mutually exclusive mutations in BRAF (50–60%), NRAS (20–25%) and NF1 (14%)." (PMID 34440905, 2021). "In subtype studies, we specifically excluded NSCLC with driver mutations and melanoma with BRAF V600E mutation, to avoid bias." (PMID 34513666, 2021). "BRAF mutation and expression have also been shown to affect the immunological phenotype of melanoma." (PMID 34123788, 2021). "BRAF mutations occur in almost all (>97%) hairy cell leukaemia, ∼50% of melanoma and conventional papillary thyroid cancers, and up to 7% of lung adenomas." (PMID 33367512, 2021). "As such, NF1 mutations together with RAS mutations and BRAF fusions, which have been described in mucosal melanomas and lead to increased activation of the MAPK pathway, are promising therapeutic targets for MEK inhibition." (PMID 35008570, 2021). "In conventional melanoma, BRAF-mutated tumors have been reported to be more aggressive than the corresponding wild-type tumors." (PMID 34571863, 2021). "The frequency of mutations in some genes was higher in the younger group; for example, the BRAF mutation, which mainly occurs in melanoma and is conducive to the generation of an immunosuppressive microenvironment, was more common in the younger group." (PMID 34249711, 2021). "The combination of MEK inhibitor with BRAF inhibitor has become the standard of care for patients with BRAF-mutated melanoma." (PMID 35069558, 2021). "Recent studies have shown that histone deacetylase (HDAC) and mutant BRAF (v-Raf murine sarcoma viral oncogene homolog B1) inhibitors synergistically kill melanoma cell lines with activating mutations in BRAF by induction of necrosis." (PMID 33909629, 2021). "Although targeted tyrosine kinase inhibitors have been used in clinical routine since 2011 with very good outcomes in BRAF V600-mutated melanoma, BRAF-mutated mCRC proved to be less sensitive to monotherapy." (PMID 34259881, 2021). "First, the BRAF inhibitors (BRAFi) vemurafenib and dabrafenib were approved as single agents for the treatment of BRAF-mutated advanced melanoma." (PMID 34069952, 2021). "These exosomes were also suitable for the detection of melanoma-specific mutations, like BRAF(V600E), helping to promptly identify patients at risk of relapse caused by residual disease." (PMID 34575876, 2021). "The combination of BRAF and MEK inhibitors has become standard of care in the treatment of metastatic BRAF V600-mutated melanoma." (PMID 34109122, 2021).
melanoma (continued). "The MEK inhibitors, such as trametinib, cobimetinib and binimetinib, combined with the BRAF inhibitors has been approved for BRAF-mutated melanoma by FDA14." (PMID 34526571, 2021). "In a small series of 19 primary cutaneous head and neck melanomas, including five melanomas of the scalp, we recently found the majority of cases to be a wild type for BRAF and NRAS, with BRAF mutations observed in only 23% of the melanomas." (PMID 33525348, 2021). "The lack of accurate diagnostic markers in response to therapeutic treatment in BRAF/NRAS-driven melanomagenesis is one of the main challenges in melanoma personalized therapy." (PMID 33723350, 2021). "The BRAF mutational assessment landscape in melanoma patients has evolved over time, and the modern scenario is characterized by the availability of several companion diagnostic and laboratory-developed tests." (PMID 33801689, 2021). "BRAF mutations were found in approximately 60% of melanomas, and the inhibitors “Vemurafenib” and “Dabrafenib” were proven to be efficient in melanoma patients with the mutation." (PMID 33680968, 2021). "Cobimetinib is approved in association with vemurafenib (or vemurafenib +atezolizumab) for melanoma with BRAF V600E or V600K mutations." (PMID 34976824, 2021). "BRAF-mutated melanoma cells demonstrated increased intracellular pH dependent on elevated NHE1 activity." (PMID 33918883, 2021). "This has been shown in BRAF mutated melanoma treated with dabrafenib in combination with trametinib, though not in RAI-R TC." (PMID 34335481, 2021). "Our functional analyses demonstrate that miR-129-5p inhibits cell proliferation, cell cycle progression and that it mediates BRAFi response in BRAF mutated melanoma." (PMID 34063443, 2021). "It is theoretically attractive to combine immunotherapy with targeted agents in progressing patients with BRAF mutation positive melanoma, but the toxicity of combined treatment has proven challenging." (PMID 34743688, 2021). "These cells can be converted to a melanoma tumor, and approximately 50% of all melanomas have a BRAF mutation." (PMID 34063139, 2021). "BRAF inhibitors are highly effective against melanoma, non-small cell lung cancer, differentiated thyroid tumor, colorectal cancer, cholangiocarcinoma, and other tumors with the BRAF V600E mutation." (PMID 33420213, 2021). "Although the presence of BRAF mutation is an attractive target of melanoma therapy, its prognostic value is still elusive." (PMID 34209415, 2021). "Although the reasons of BRAF-i resistance are numerous and multiple, and sometimes molecularly very distant, this information provides the basis for the combination of immunotherapy and target-therapy in BRAF-mutated melanoma." (PMID 35008245, 2021). "BRAF mutations in ctDNA of late-stage melanoma patients were consistent with more than 75% of BRAF mutated tumors." (PMID 34575876, 2021). "The coBRIM trial exhibited that first-line vemurafenib combined with cobimetinib improved progression-free and overall survival compared with vemurafenib in patients with BRAF V600-mutated advanced melanoma." (PMID 34804979, 2021). "Reactivation of the MAPK pathway has been proposed to be a major mechanism underlying the resistance of melanoma cells to BRAFi, and the combination of BRAF and MEK inhibition." (PMID 34304249, 2021). "In about half of all melanoma patients, tumor growth is driven by gain-of-function mutations of BRAF (v-rat fibrosarcoma (Raf) murine sarcoma viral oncogene homolog B), which results in constitutive ERK activation." (PMID 34576054, 2021). "Vemurafenib is a BRAF kinase inhibitor (BRAFi) that is used to treat melanoma patients harboring the constitutively active BRAF-V600E mutation." (PMID 33604667, 2021).